TNC (tenascin C)
Diseases named in the same sentence as TNC in open-access papers (continued):
Sharing a sentence is not in itself a finding about the gene and the disease.
schizophrenia (1 paper, 2023). A major psychotic disorder characterized by abnormalities in the perception or expression of reality. "In addition, almost no studies have discussed the relationship between Tenascin C and psychiatric disorders, making it difficult to discuss the significance of reduced Tenascin C in the prefrontal cortex (BA10) of schizophrenia patients." (PMID 37143779, 2023). "Among the 7 DEGs, the TNC gene was the only gene that decreased with schizophrenia and showed a positive correlation with PI (16:0/20:4), while the other 6 DEGs (COL1A2, COL6A2, DDIT4, FGF17, GNB3, and PDGFRB) increased with schizophrenia and showed a negative correlation with PI (16:0 /20:4)." (PMID 37143779, 2023).
scoliosis (1 paper, 2021). A congenital or acquired spinal deformity characterized by lateral curvature of the spine. "Inherited fast TnC (TNNC2) missense mutations led to scoliosis and respiratory weakness at birth among members of two families studied, though the condition appears to improve over time and suggests a compensatory effect of cardiac/slow TnC with increased reliance on slow twitch fibers with age." (PMID 34733179, 2021).
Seizure (1 paper, 2019). A seizure is an intermittent abnormality of nervous system physiology characterized by a transient occurrence of signs and/or symptoms due to abnormal excessive or synchronous neuronal activity in the brain. "Seizure upregulates the expression of multiple ECM molecules, including tenascin-C, tenascin-R, neuronal pentraxin 2, and hyaluronan." (PMID 31827499, 2019).
skin aging (1 paper, 2020). The gradual irreversible changes in structure of skin that occur as a result of the passage of time.. "Based on these results, we hypothesize that TNC is an important molecule involved in intrinsic skin aging by modulating ECM integrity." (PMID 33217999, 2020). "Based on our findings, we suggest that TNC is an important molecule that maintains the ECM integrity and prevents and attenuates skin aging." (PMID 33217999, 2020).
stromal dystrophy (1 paper, 2012). "Immunolocalization of fibrillin-2, matrilin-2, matrilin-4, and tenascin-C in normal and stromal dystrophy corneas (maximum and minimum gray levels are 0 and 255, respectively)." (PMID 22876117, 2012). "The present study investigated the expression patterns of fibrillin-2, tenascin-C, matrilin-2, and matrilin-4 in granular and lattice type I corneal stromal dystrophy samples." (PMID 22876117, 2012).
thyroid tumor (1 paper, 2025). A benign or malignant neoplasm affecting the thyroid gland. "Finally, we explored the role of TNC in thyroid tumor growth and invasion in vivo." (PMID 39951495, 2025).
tongue cancer (1 paper, 2020). A malignant neoplasm affecting the tongue. "Moreover, the expression of the extracellular matrix proteins tenascin c and fibronectin discriminates low- and high-risk tongue cancers." (PMID 33344431, 2020).
Ureteral obstruction (1 paper, 2022). Obstruction of the flow of urine through the ureter. "Genetically deletion of TNC in mice significantly attenuated unilateral ureteral obstruction-induced kidney fibrosis." (PMID 36522320, 2022). "To further examine the expression of TNC in kidney fibrosis, we generated a unilateral ureteral obstruction (UUO) mouse model and found that TNC protein and mRNA were significantly increased in the fibrotic kidneys." (PMID 36522320, 2022).
urothelial carcinoma (1 paper, 2020). A malignant neoplasm derived from the transitional epithelium of the urinary tract (urinary bladder, ureter, urethra, or renal pelvis). "It is reported that the expression level of TNC was increasing in invasive tumor cells, but the prognostic significance of TNC in urothelial carcinoma (UC) needs further investigation." (PMID 32640634, 2020).
vulvar cancer (1 paper, 2023). "Tenascin-C was also higher in vulvar cancer-draining nodes (8.318 ± 10.816), compared to endometrial (2.463 ± 3.88) or cervical (0.889 ± 1.269) cancer-draining lymph nodes (p = 0.0007 and 0.037, respectively)." (PMID 36835583, 2023).
tumor (474 papers, 1998 to 2026). "Tumour cells can instruct CAFs through paracrine signalling, and CAFs can promote epithelial-mesenchymal transition (EMT) by secreting factors such as tenascin-C, while tumour budding is strongly associated with EMT." (PMID 41454575, 2026). "In the relma-cel study, the expression levels of tumor-associated fibroblast markers (AP, TNC, CSPG4, PDGFRA, S100A4, ASPN, STC1, and ITGAM) were higher in the patients with PR than with CR." (PMID 39858099, 2025). "Similar to what we observed for the MYBL1 gene, exons 14 and 16 of the Tenascin-C gene are considered tumor-associated regions of the gene that affect invasive properties of the gene in breast cell lines." (PMID 39796135, 2024). "This study identifies a novel integrin binding competition between pGSN and TNC, and GSN gene methylation during ESCC tumor progression causes decreased secretion of pGSN, leading to integrin αvβ3 dysregulation, oncogenic TNC activation, and CAF formation." (PMID 39261905, 2024). "The ECM was found to be involved in CD47-mediated macrophage phagocytosis signaling through the expression of the tumor-associated extracellular matrix protein tenascin C (TNC)." (PMID 39033204, 2024). "In glioblastomas, TNC is expressed in the tumor and stromal cells, and its high expression is associated with tumor progression and poor prognosis." (PMID 38331927, 2024). "CDH2, SPP1, and TNC maintained a statistically significant increase associated with the progression of individual cancer stages in LUAD tumor samples compared to their respective controls." (PMID 37887075, 2023). "Tenascin-C (TNC), encodes a matricellular protein, is abundantly expressed in both inflammatory lesions and tumor tissues." (PMID 37664052, 2023). "In a bladder cancer model, tumor-derived EVs induced tenascin-C expression by fibroblasts, and this is associated with a worse prognosis." (PMID 38067320, 2023). "Other studies have found that tumor-associated macrophages secrete TNC and FN1and both proteins were among the most enriched in the macrophage secretome." (PMID 38264656, 2023). "Tenascin C levels are elevated in the cancer-associated stroma, and they can inhibit the interaction between syndecan 4 and FNs, thus promoting tumor growth and metastasis." (PMID 37350937, 2023). "Most of these genes were tumor cell metastasis-associated genes such as TNC, PLAU, PDPN, SPARC, LUM, and especially SNAI2 (Zinc finger protein SLUG transcription factor)." (PMID 35742914, 2022). "CD47 knockout increased tumor-associated extracellular matrix protein tenascin C (TNC) in U87 intracranial xenografts." (PMID 35967394, 2022). "It has been reported that TNC expression limited only to the stroma is associated with better prognosis than its expression in both stromal and tumor cells." (PMID 35268340, 2022). "TNC is also expressed in malignant tissues, particularly upon initiation of angiogenesis, and its expression, both in cancer-associated stroma and tumor cells, has been associated with a poor clinical outcome." (PMID 33562105, 2021). "The tumor ECM was shown to be intricately linked to CD47-mediated macrophage phagocytosis signaling through the expression of tumor-associated extracellular matrix protein tenascin C (TNC)." (PMID 34571905, 2021). "Using nanoparticle delivery (including liposomes and extracellular release strategies), tenascin-C targeting has been used to deliver drugs towards tumor cells as well as cancer-associated fibroblasts." (PMID 33572559, 2021). "TNC upregulation at the invasive tumour front has already been associated with poor clinical outcome suggesting its role in metastatic progression." (PMID 33739025, 2021). "Other examples of paracrine secretion of TnC in exosomes include osteoblasts, airway epithelial cells and several tumor cells, where exosomal TnC has been associated to alterations of pre-existing ECM, impacting collagen and alkaline phosphatase activity." (PMID 33981316, 2021).
tumor (continued). "TNC over-expression is repeatedly observed in cancer, often at the invasive tumor front, and associates with poor clinical outcome in several malignancies, including UADT SCC." (PMID 34199373, 2021). "The loss of CD47 function upregulates the tumor-associated extracellular matrix protein tenascin C (TNC) expression in tumor cells via a Notch pathway-mediated mechanism." (PMID 34071306, 2021). "In the tumor stroma of most epithelial malignancies, there is an increased deposition of TNC, which is associated with a poor prognosis." (PMID 33564303, 2021). "Instead, the ccRCC ECM is composed largely of collagen VI, fibronectin, and tenascin C. Analysis of single cell expression data indicates that cancer-associated fibroblasts are a major source of tumor ECM production." (PMID 34884982, 2021). "TNC has a variety of pro-tumorigenic interactions with cancer cells, cancer-associated fibroblasts, lymphocytes and tumour-associated macrophages, as well as angiogenesis promoting interactions with endothelial cells." (PMID 34205668, 2021). "Among the proteins known to be specifically expressed in tumor-associated stroma are tenascin-C and tenascin-W." (PMID 31032255, 2019). "The high levels of TNC expression in gastric GISTs was significantly associated with tumor size (P < .001), multivisceral resection (P = .006), metastasis at initial diagnosis (P = .006), mitotic count (P = .002) and NIH risk classification (P = .015)." (PMID 30633201, 2019). "We previously found that a peptide derived from the tumor-associated type III-A2 domain of the tenascin-C molecule, termed TNIIIA2, is capable of inducing conformational change in β1-integrins that are necessary for its functional activation." (PMID 31261783, 2019). "Metastasis-associated lung adenocarcinoma transcript 1 (MALAT1) upregulation induced by Yes-associated protein (YAP) activation was responsible for TNC-regulated ES tumour progression." (PMID 31649319, 2019). "We previously found that peptide TNIIIA2, which is derived from the tumor-associated tenascin-C variants, has the ability to promote cell adhesion by activating β1-integrins." (PMID 31261783, 2019). "Certain tenascin-C splice variants containing additional FNIII domains are more tumor-specific than the shortest isoform, and isoform-specific antibodies against tenascin-C can be used as tumor markers." (PMID 31032255, 2019). "In multiple tumor types, TNC over-expression is associated with tumor cell proliferation and decreased adhesion." (PMID 31092287, 2019). "Tenascin-C expression in the tumor bulk stroma associated to cancer survival in the univariate analysis, high expression indicating poor prognosis (log rank p=0.034)." (PMID 28978001, 2017). "Tenascin-C expression in the tumor bulk stroma was associated with several clinocopathological variables including high T-class (p=0.006), lymph node (p=0.004) and organ metastases (p=0.007)." (PMID 28978001, 2017). "Several previous studies have demonstrated that the high tenascin-C expression in the tumor microenvironment is caused by its increased synthesis in myofibroblasts." (PMID 28978001, 2017). "Tenascin-C expression was generally more abundant than fibronectin and high Tenascin-C expression in the tumor stroma significantly associated with advanced TNM-stage and poor prognosis." (PMID 28978001, 2017). "Elevated Tenascin-C serum values are associated with larger tumor size and lymph node involvement (p=0.022 and p=0.036, respectively)." (PMID 26967391, 2016). "Tenascin C expression correlates significantly with tumor proliferation, especially in RET-mutated tumors." (PMID 27409604, 2016). "Tenascin C correlated significantly with tumor proliferation (overall, r = 0.61, p < 0.005; RET-mutated, r = 0.81, p < 0.01)." (PMID 27409604, 2016). "Tenascin-C expression in cancer cells was correlated with an increase in tumor-associated macrophage (TAM) population, cancer recurrence, and hypoxia inducible factor1α (HIF1α) expression." (PMID 26731558, 2016).
tumor (continued). "Numerous proteins that constitute the ECM show a close association with tumor tissue, such as Tenascin-C (TN-C) and Matrix metalloproteinases (MMPs)." (PMID 26652622, 2015). "Statistical analysis was performed using a nonparametric Mann-Whitney test for comparison of clinicopathological features with levels of TNC expression and using Jonckheere-Terpstra trend analysis for association of expression with tumour grade." (PMID 20678196, 2010). "TNC promotes angiogenesis and can induce expression of matrix metalloproteinases, which themselves have been implicated in promoting tumour growth and invasion." (PMID 20678196, 2010). "This raises the possibility that tumour-associated stroma can generate novel interactions with tumour cells through the expression of different TNC splice variants." (PMID 19405959, 2009). "Additionally, Tenascin-C, a glycoprotein associated with tumor growth and metastasis, was markedly higher (p < 0.0001) in the ASC secretome compared to SKOV3-derived CM." (PMID 40072102, 2025). "Further research into the molecular mechanisms underlying DIPG tumorigenesis, including the role of Tenascin-C in tumor progression and the influence of H3K27M mutations on oligodendroglial precursor cells, is necessary to identify novel therapeutic targets and improve patient outcomes." (PMID 38791893, 2024). "Another question is whether the expression of oncofetal FNs and TNC results from oncogenic mutations or is induced by components like TGFβ in the tumor microenvironment, as observed with oncfFN in human prostate epithelial cell lines." (PMID 38660622, 2024). "In a recent study, glycan-associated proteins such as CD147, BGN, VCAN, and TNC were found to be enriched in tumor EVs compared to EVs secreting from non-tumor adjacent tissues, which can be potentially used as cancer EV biomarkers or even to identify the cancer origin." (PMID 37773167, 2023). "Furthermore, NG2 has been demonstrated to enhance tumor cell invasion and metastasis through β-1 integrin activation 41, while Tenascin-C has been linked to tumor invasiveness and metastatic progression." (PMID 36860926, 2023). "These tumor-associated stromal cells also secrete a number of pro-tumorigenic factors, such as stromal-derived factor-1α, IL-6, IL-8, vascular endothelial growth factor, matrix metalloproteinases, and tenascin-C." (PMID 36271354, 2022). "As in tumors the large isoform of TNC is highly expressed and was shown to be associated with an inflammatory pro-tumorigenic function future studies have to address the potential roles of the different forms of TNC in the irradiated tumor tissue." (PMID 34290694, 2021). "Increased levels of TNC in vivo in a mouse model of GBM was associated with reduced T cell enrichment in tumor tissue on histologic analysis, and assessment of in vivo transmigration using a mouse air pouch model demonstrated TNC-mediated transmigration of T cells." (PMID 35127517, 2021). "Together, our findings reveal TNC expression in DIPG in association with H3K27 M mutation and VEGF signaling, and suggest that TNC may contribute to DIPG tumor phenotype, and serve as a clinically detectable biomarker for DIPG." (PMID 31092287, 2019). "TNC overexpression is associated with more malignant cell behavior, including increased cell proliferation and migration, and patterns of gene expression consistent with a pro-angiogenic, mesenchymal tumor phenotype." (PMID 31092287, 2019). "In summary, our study demonstrates that MALAT1 upregulation induced by integrinα5β1-mediated YAP activation may be responsible for TNC-regulated tumour progression in ES and that TNC overexpression is associated with poor survival in ES patients." (PMID 31649319, 2019).
tumor (continued). "Whereas, tumour associated immune cells (TAMS), tumour associated fibroblasts (e.g., FAP, α-SMA, FGFRs, tenascin-C and thrombospondin-1) and tumour initiating stem cells (e.g., CD133, EpCAM and aldehyde dehydrogenases), have been utilised to allow for NPPSs drug targeting within a TME." (PMID 30322132, 2018). "The large tenascin-C variant is preferentially expressed in malignant tissues, is spatially and temporally related to tumor neovascularization and may exert anti-adhesive, and immunosuppressive activities." (PMID 29515769, 2018). "Further, our results suggest that TNC-regulated expression of cellular FN contributes to the temporally ordered changes in matrix composition that impact vascular stability and maturation during development and dynamic remodelling of tumour-associated vessels." (PMID 28986537, 2017). "Several aptamers developed against microorganisms, such as Trypanosoma cruzi excreted secreted antigens (TESA), and human cells, such as U88 glioma cells expressing epidermal growth factor receptor variant III, or tumor cells expressing tenascin-C were confirmed through enzyme-linked assays." (PMID 29186905, 2017). "Hypoxia is a characteristic of abnormal tumor microenvironment, and is intrinsically linked to the formation of neovasculature and clinically associated with metastasis and poor patient outcome; furthermore, it can induce Tenascin-C expression." (PMID 26731558, 2016). "The correlation of clinico-pathological data with Tenascin-C using cross tabulation showed a significant association of increased Tenascin-C and tumor sizes (pT3 and pT4 compared to pT1 and pT2 p = 0.022) and the status of the lymph nodes (pN2 and pN3 versus pN1; p = 0.036), respectively." (PMID 26967391, 2016). "Tenascin-C is overexpressed in the stroma of most solid malignancies and may function as a diagnostic tumor marker." (PMID 26967391, 2016). "Tenascin C correlates significantly with tumor proliferation, especially in RET-mutated tumors." (PMID 27409604, 2016). "In addition to histological vessel malformations, tumor vessels show an anomalous composition of their ECM, for example, tenascin-C and –W, and the oncofetal fibronectin ED-B splice variants are associated with tumor vessels." (PMID 21941547, 2012). "In addition to fibronectin, tenascin-C and osteopontin expression in the tumor stroma is associated with enhanced lymph node metastasis, and LECs upregulate tenascin-C expression during lymphangiogenesis." (PMID 22505936, 2012). "Centyrins are small (∼ 10 kDa) cysteine-free scaffolds based on the type-III fibronectin domain of human Tenascin C. These alternative scaffolds possess excellent biophysical properties, which allow for mutation and conjugation at one or even multiple positions and are easily internalized by tumor." (PMID 33509252, 2021). "One of the major mechanisms by which thrombospondin-1 regulates tumor outgrowth and dormancy is by interacting with the latency associated peptide in complex with TGFβ to release TGFβ into the local environment and thereby stimulate TGFβ signaling (see Tenascin-C above)." (PMID 33014869, 2020). "Indeed, TNC overexpression driven by EWS-FLI1 in the tumour-associated microenvironment may play an enhanced role in persistently promoting ES to metastasise to distant organs." (PMID 31649319, 2019). "Our findings reveal increased TNC expression in DIPG tumor specimens relative to controls, in association with H3K27 M mutation and VEGF signaling, and suggest that TNC expression may serve as a clinically detectable biomarker for treatment stratification and measuring response to therapy." (PMID 31092287, 2019). "However, although elevated TNC serum levels have been found previously in various cancers in agreement with our study, no predictive or prognostic roles have been associated to them in other studies, questioning TNC’s role as a tumor marker." (PMID 27612200, 2016).